RN7SL546P (RNA, 7SL, cytoplasmic 546, pseudogene)
Gene: Miscellaneous RNA gene on chromosome 14 (102,582,888 to 102,583,177, reverse strand). Ensembl gene ENSG00000239224.
Homologues: Orthologues: chimpanzee Metazoa_SRP (92% identical), macaque Metazoa_SRP (89% identical). Paralogues in human: RN7SL1 (86% identical), RN7SL2 (86% identical), RN7SL3 (85% identical), RN7SL296P (83% identical), RN7SL679P (82% identical), RN7SL126P (82% identical), RN7SL597P (82% identical), RN7SL664P (82% identical), RN7SL480P (81% identical), RN7SL650P (81% identical), RN7SL220P (81% identical), RN7SL478P (81% identical), and 702 more.